ADM (adrenomedullin)
Diseases named in the same sentence as ADM in open-access papers (continued):
Sharing a sentence is not in itself a finding about the gene and the disease.
cancer (67 papers, 2003 to 2025). A tumor composed of atypical neoplastic, often pleomorphic cells that invade other tissues. "ADM, a peptide involved in various physiological processes including vascular health and hormone regulation, has been implicated in cancer progression by promoting proliferation, angiogenesis and metastasis." (PMID 40074697, 2025). "Another pathway is the CALCR pathway with the ADM-CALCRL communication, the macrophages and cancer-associated fibroblasts signal the endothelial cells via ADM secretion, suggesting the promotion of angiogenesis." (PMID 39149248, 2024). ", reveal that MCF-7 mammospheres produce ADM, which modifies the phenotype of cancer-associated adipocytes via the ADM receptor in a paracrine manner." (PMID 38060103, 2023). "In total, nine inflammation and cancer-associated DEGs were selected to show their changed expression patterns, comprising four up-DEGs (ADM, FSTL3, SPDEF, and SPNS2) and five down-DEGs (TACSTD2, CCL2, EDIL3, FAM20C, and OLFML2A)." (PMID 37953789, 2023). "Unexpectedly, the clinical study revealed that high expression of ADM was linked to positive outcome and to cancer with low Ca125." (PMID 22859951, 2012). "A forest plot illustrated the risk associated with high ADM expression in various cancers." (PMID 40529377, 2025). "Additionally, using the GEPIA database, this study explored the association between ADM expression and cancer stage." (PMID 40529377, 2025). "Interestingly, cancer-associated PSC-derived exosomes have also demonstrated the presence of adrenomedullin." (PMID 34680372, 2021). "Consequently, ADM is implicated in the pathophysiology of various cancers." (PMID 40565016, 2025). "This review summarizes the contribution of ADM to tumorigenesis and development and its potential functions in cancer therapy." (PMID 40565016, 2025). "A better understanding of the relationship between ADM and cancer can provide a foundation for clinical applications and open up new strategies for treating cancer patients by targeting ADM." (PMID 40565016, 2025). "Multiple other mechanisms likely contributed to the aberrant expression of ADM in different cancer types." (PMID 40529377, 2025). "Genetic alterations in ADM were observed in 0.8% of 10,967 samples from 10,953 patients with various cancer types." (PMID 40529377, 2025). "We also added blocking antibodies against VEGFR3, TGF-β, EGF, PDGF, and adrenomedullin to cancer cells before starting CM generation, which was subsequently transferred to the HLECs." (PMID 41249124, 2025). "Mechanistically, ADM overexpression in cancer cells enhances neovascularization, thereby facilitating macroscopic metastatic outgrowth, particularly after initial entrapment in lymphatic vessels." (PMID 40547013, 2025). "In recent years, an expanding body of research has demonstrated that ADM plays a pivotal role in the initiation and progression of various cancers." (PMID 40565016, 2025). "Our study further presented that ADM expression was correlated with advanced pathological stages in cancers such as THCA, PAAD, LUAD, LIHC, KIRP, and HNSC, suggesting its role in disease progression." (PMID 40529377, 2025). "These cells contribute to the secretion of ADM, thereby facilitating the growth and metastasis of malignant tumors." (PMID 40565016, 2025). "While the involvement of ADM in cancer pathogenesis has been extensively investigated, there remain many gaps in the literature on the subject." (PMID 40565016, 2025). "Adrenomedullin (ADM) is a multifunctional peptide that plays a pivotal role in various pathological processes, particularly in cancer progression." (PMID 40529377, 2025). "In accordance with the documented role of adrenomedullin in various cancers, we observed that high expression of ADM is a common feature among NDMM patients." (PMID 38690165, 2024). "ADM is upregulated in a variety of human cancers compared with normal tissues and its mRNA expression correlated with high protein expression in the majority of them." (PMID 34150648, 2021).
cancer (continued). "Cancer-cell derived exosomes containing adrenomedullin have also been shown to increase lipolysis in both mouse and human adipocytes, supporting adrenomedullin as a possible mediator of PDAC-associated metabolic alterations." (PMID 34680372, 2021). "They support the cancer cells by proceeding angiogenesis via adrenomedullin and secretion of vascular epithelial growth factors (VEGFs) while its immunosuppression function is mediated by expression of IL-10, PD-L1 (programmed death-ligand 1), and TGFβ." (PMID 34335844, 2021). "We identified that cancer cells in mammospheres, through ADM secretion, were able to modify the phenotype of adipocytes." (PMID 32819314, 2020). "Their study demonstrated that the peptide adrenomedullin promotes coupling of cancer cells to LEC gap junctions and facilitates heterocellular communications to induce transendothelial migration." (PMID 32002106, 2020). "A number of gene nodes linked to drug resistance in other cancer types (including CAT, TRIM59, ANXA2, ADM, AJUBA, HSPA1A/1B, LAMC2, TRIM14, KRT8, KRT18, KRT9, CLDN1, and SMARCA2) were also down-regulated in PARPis-sensitive AsPCs." (PMID 33213473, 2020). "The ROC curves uncovered that ADM in plasma had a good sensitivity and specificity to distinguish cancer patients from healthy people." (PMID 27391260, 2016). "The adrenomedullin peptide (ADM) is considered a proto-oncogene that plays multiple roles in cancer." (PMID 24961511, 2014). "Increased expression of circulating ADM in cancer patients has also previously been described for colon and lung malignancies." (PMID 14612905, 2003). "Additionally, the positive correlations between ADM and CD4+ T cells and macrophages were observed across the majority of cancer types, further supporting the potential role of ADM in immune regulation." (PMID 40529377, 2025). "In summary, the role of ADM in tumorigenesis and cancer progression is complex and multifaceted." (PMID 40565016, 2025). "However, it was noteworthy that among these immune-related genes, CD274, CD276, TNFRSF18, TNFSF9, and PVR displayed strong correlations with ADM expression across almost all cancer types." (PMID 40529377, 2025). "Notably, this study explored the relationship between ADM expression and immune-related genes across a range of cancer types, identifying distinct correlation patterns." (PMID 40529377, 2025). "Based on the pan-cancer analysis of drug sensitivity datasets, ADM and ADM2 expression levels were significantly correlated with sensitivity of various medications in both the GDSC and CTRP databases, with ADM showing a broader and more significant correlation." (PMID 40529377, 2025). "In addition, ADM exhibited genetic alterations, including amplification and deep deletion across multiple cancer types." (PMID 40529377, 2025). "Hence, ADM appears to be crucial in controlling the interactions between cancer cells and adipocytes and represents an excellent target to hinder them." (PMID 32819314, 2020). "Based on adrenomedullin upregulation in hypoxia, and its effect on angiogenesis as well as prevention of apoptosis, studies have been conducted to evaluate its usefulness in cancer treatment." (PMID 28620317, 2017). "In summary, we demonstrated that blocking the ADM receptor inhibited proliferation of sunitinib-resistant RCC cells via the ERK/MAPK pathway, supporting the hypothesis that ADM can exert autocrine/paracrine effects promoting cancer growth in RCC." (PMID 27556517, 2016). "Adrenomedullin is an important endocrine and neurocrine integrator of homeostasis in the vascular system, performing diverse important functions in physiogenesis and pathogenesis, including angiogenesis and cancer." (PMID 25694747, 2015). "The results of the present study suggest that ADM plays an important role in ICC metastasis, and that ADM signaling of EMT may represent a valuable therapeutic target in cancer patients." (PMID 26043778, 2015).
cancer (continued). "Thus, ADM appears to play a critical role in modulating the interactions between cancer cells and adipocytes, suggesting that it may serve as a promising therapeutic target for disrupting these interactions." (PMID 40565016, 2025). "Consequently, the ADM signaling pathway emerges as a promising target for anti-cancer strategies." (PMID 40565016, 2025). "Besides the modification of adipocyte metabolism, the role of ADM in cancer progression may be multifactorial." (PMID 32819314, 2020). "MIG secreted from pumc-91/ADM-exposed DCs might trigger cancer migration and invasion." (PMID 27556503, 2016). "This research revealed strong positive correlations of ADM with CD4+ T cells, macrophages, and B cells in cancers such as LUAD and MESO, supporting ADM’s role in recruiting and activating immune cells." (PMID 40529377, 2025). "The expression of SLC6A8 exhibited the strongest positive correlation with that of ADM, GPI, NDRG1, PGK1, and PNCK, and their correlation with SLC6A8 expression in distinct cancer types were illustrated by the heatmap, respectively." (PMID 36061183, 2022). "Not only are procalcitonin/adrenomedullin neuropeptides found in GBM, but they are also found in 16 other cancers." (PMID 35052689, 2021). "Among the top 10 genes upregulated in adipocytes, adrenomedullin (ADM) is a cytokine known to be secreted by adipocytes, and has been shown to play a role in cell survival in several types of cancer." (PMID 27705905, 2016). "Strong and consistent positive correlations were witnessed between ADM and several immune checkpoint genes, including CD274 (PD-L1), CD276, TNFRSF18, TNFSF9, and PVR in pan-cancer analysis, indicating its role in the development of suppressive immune microenvironment and T cell exhaustion." (PMID 40529377, 2025). "This study found significantly negative correlation between DNA methylation and ADM mRNA expression in several cancer types, particularly in SKCM." (PMID 40529377, 2025). "Furthermore, the inhibitory effects of knocking down ADM and POLR1D expression on cancer-related biological behaviors in CAL-27 and SAS cells were experimentally validated." (PMID 38256104, 2024). "The roles played by the peptides belonging to the tachykinin (neurokinin A and B) and calcitonin/calcitonin gene-related peptide (adrenomedullin, adrenomedullin 2, amylin, and calcitonin gene-related peptide (CGRP)) peptide families in cancer development are reviewed." (PMID 36980580, 2023). "Therefore, the emerging understanding of the involvement of exosomal ADM in adipose tissue interactions and lipolysis within the TME offers a perspective on the intricate crosstalk among cancer cells, and adipocytes, and their mutual influence." (PMID 38060103, 2023). "Among the commonly upregulated LD+ associated genes in GBM cells and patient tumors, we found several hypoxia-related, key effectors of angiogenesis, macrophage recruitment and stromal remodeling in cancer (e.g. VEGF-A, TGF-β1, IL1β, ADM, IGFB3, LOX, CA9, THBS1, PLODs, ID2)." (PMID 31174567, 2019). "The similarities between IMD and adrenomedullin have raised the possibility that IMD may also have a role in angiogenesis and cancer." (PMID 25694747, 2015). "After culturing cancer cells under stressing conditions, such as serum starvation and/or hypoxia, ADM was found to be a survival factor in HEY but not in other cell lines." (PMID 22859951, 2012). "Thus, ADM is a key factor linking macrophage polarization and ovarian cancer cell migration, highlighting its potential as a therapeutic target to inhibit TAM-mediated cancer progression." (PMID 40330466, 2025). "ADM was found to exhibit a strong and consistent positive correlation with several immune checkpoint genes, including CD274 (PD-L1), CD276, TNFRSF18, TNFSF9, and PVR in the pan-cancer analysis, which contributed to the development of a suppressive immune microenvironment." (PMID 40529377, 2025).
cancer (continued). "However, in most cancer types, ADM expression did not exhibit significant correlation with corresponding DNA methylation." (PMID 40529377, 2025). "However, ADM were not differentially expressed between LUAD-normal and LUAD-cancer." (PMID 35957802, 2022).
cardiovascular disease (26 papers, 2007 to 2026). "Adrenomedullin is a prognostic biomarker in several cardiovascular diseases and was recently shown to associate with hemodynamic instability in patients with septic shock." (PMID 28050899, 2017). "GrimAge is based on seven plasma protein levels related to various diseases and conditions, including cardiovascular disease (Plasma B2M) and cognitive functions (Plasma B2M, ADM, Cystatin C, and leptin)." (PMID 40699219, 2025). "Adrenomedullin has been proposed as a predictive marker of mortality in several types of cardiovascular disease." (PMID 39200990, 2024). "ADM antibodies are emerging as a promising therapeutic approach in the treatment of cardiovascular disorders." (PMID 39200990, 2024). "In patients with cardiovascular diseases, ADM is significantly up-regulated in the epicardial adipose tissue." (PMID 37662558, 2023). "A potentially new marker of cardiovascular diseases — proadrenomedullin is the precursor of adrenomedullin, which is a multifunctional peptide hormone, produced in most of the tissues in response to cellular stress, ischemia, and hypoxia." (PMID 35522058, 2022). "This is consistent with our previous observation that the antioxidative stress action of adrenomedullin plays an important role in organ protection in cardiovascular disease." (PMID 23957015, 2013). "Also, there is compelling evidence linking increased plasma and tissue levels of ADM with cardiovascular disease." (PMID 37637145, 2023). "CGRP and ADM are potent vasodilators with ameliorating effects on cardiovascular disease." (PMID 32358547, 2020). "Its role in blood pressure regulation has been examined in numerous studies, which demonstrated that adrenomedullin could be a promising biomarker for cardiovascular disease in the future." (PMID 31048758, 2019). "Adrenomedullin (ADM) and adiponectin are both involved in inflammation and cardiovascular diseases." (PMID 23936408, 2013). "This enhances our understanding of the regulation of ADM level and points to the close interplay between these two hormones that could be very important in cardiovascular diseases." (PMID 23936408, 2013). "Given the important roles of ADM and adiponectin in cardiovascular diseases, knowing the interactions between these two peptides may help to refine the interpretation of the levels of these biomarkers, and may even suggest new therapeutic approaches in combating these diseases." (PMID 23936408, 2013). "The data shown here investigates an antiparallel triplex, formed between the lncRNA hypoxia-inducible factor 1-alpha Antisense RNA 1 (HIF1α-AS1) and the DNA target Adrenomedullin (ADM), important in cardiovascular diseases." (PMID 42086308, 2026). "MMPs are known to play an important role in cardiovascular diseases through different mechanisms, including ECM remodeling, promoting VSMCs migration by cleaving cadherin, and increasing vasoconstriction via cleaving vasoactive precursors such as endothelin-1 and adrenomedullin." (PMID 36552622, 2022).
infection (24 papers, 2006 to 2025). The state of being infected such as from the introduction of a foreign agent such as serum, vaccine, antigenic substance or organism. "Therefore, impaired removal of circulating ADM in the pulmonary circulation resulting from infection-associated lung injury may partly contribute to the elevation of plasma ADM levels." (PMID 19627611, 2009). "Therefore, impaired removal of circulating ADM during pulmonary circulation resulting from infection-associated lung injury may partly contribute to the elevation of plasma ADM levels." (PMID 16805922, 2006). "The downregulated genes associated with the ADM pathway included MAPKs, PLCs, the PIK3R2, the guanylate cyclase C, implicated in infection and inflammation control and the IL1RN, which encodes the anti-inflammatory protein IL-1Ra." (PMID 38241313, 2024). "Adrenomedullin seems to be useful in the pediatric population for a large variety of pathologies, especially regarding infection and cardiovascular conditions." (PMID 36010070, 2022). "In recent years the mid-regional pro-adrenomedullin (MR-proADM), the 45–92 amino-acid sequence of adrenomedullin (ADM), has been proposed as a marker of infection alone or in combination with PCT." (PMID 30102716, 2018). "A newer candidate biomarker for infection includes pro-Adrenomedullin, which levels correlate with severity of infection and accurately distinguish infection from inflammation, especially in febrile neutropenic children." (PMID 30572918, 2018). "Endothelin-1 and adrenomedullin precursor peptides gradually increase with increasing severities of infection in critically ill patients." (PMID 18080871, 2007). "Research on adrenomedullin has primarily been related to infection and the cardiovascular field." (PMID 36010070, 2022). "Consistent with our findings in humans, the levels of ADM mRNA and protein were almost only detected in WT H. pylori-infected mice, reaching a peak 21 days post infection (p.i.), indicating that a role for cagA is involved in the induction of ADM in gastric mucosa during H. pylori infection." (PMID 32184393, 2020). "Consistently, elevated bio-ADM levels at baseline were associated with higher disease severity, as expressed in higher SOFA and APACHE scores, higher incidence of organ (in particular renal) dysfunction, and with higher levels of markers of infection and inflammation (PCT and CRP)." (PMID 40447978, 2025). "Moreover, H. pylori-infected AGS cells could increase ADM mRNA expression and ADM protein production in a time-dependent and infection dose-dependent manner." (PMID 32184393, 2020). "Bioactive adrenomedullin (bio-ADM) is a vasoactive peptide with a key role in reducing vascular hyperpermeability and improving endothelial stability during infection, but it also has vasodilatory properties." (PMID 36864354, 2023). "MR-proADM, derived from adrenomedullin (ADM), has been shown to play a role in preserving the integrity and stability of the endothelium after severe infection." (PMID 36941681, 2023). "Thus, biomarkers of inflammation or infection, such as procalcitonin (PCT), C-reactive protein (CRP), interleukin-6 (IL-6), neopterin, and pro-adrenomedullin (pro-ADM), have a significant role in the diagnosis and management of sepsis." (PMID 33810263, 2021). "A possible reason for pro-adrenomedullin being the most predictive of death, ICU admission, and high initial triage priority is that inflammation is inclusive of a greater number of conditions than infection." (PMID 28497010, 2017). "However, novel biomarkers for bacterial or fungal sepsis, such as procalcitonin or adrenomedullin have shown promising sensitivity and specificity in identifying infection, but, to our knowledge, have not been studied specifically in the context of CRS, yet." (PMID 40277755, 2025).
infection (continued). "Clearly, on diagnosis of the infection patients with CVF presented higher levels of PCT, IL-6, pro-adrenomedullin and suPAR, regardless of the duration; however, at day 3 after diagnosis, high biomarker levels were found only in patients with persistent CVF." (PMID 34209181, 2021).
bacterial infection (7 papers, 2010 to 2024). "Pro-adrenomedullin and procalcitonin showed statistically significant high values in patients with bacterial infections." (PMID 31206538, 2019).